7SK (7SK RNA )
Synonyms: RN7SK
Gene: Miscellaneous RNA gene on chromosome 6 (52,995,620 to 52,995,950, forward strand). Ensembl gene ENSG00000202198.
Homologues: Orthologues: mouse Rn7sk (99% identical), guinea pig 7SK (98% identical). Paralogues in human: RN7SKP118 (90% identical), RN7SKP187 (88% identical), RN7SKP227 (88% identical), RN7SKP48 (88% identical), RN7SKP174 (88% identical), RN7SKP185 (87% identical), RN7SKP62 (86% identical), RN7SKP178 (85% identical), RN7SKP76 (84% identical), RN7SKP292 (83% identical), RN7SKP55 (82% identical), RN7SKP160 (79% identical), and 284 more.
Diseases named in the same sentence as 7SK in open-access papers:
7SK is named in the same sentence as 12 diseases in open-access papers, as found by Europe PMC text mining. Sharing a sentence is not in itself a finding about the gene and the disease. The quoted sentences say what the papers report.
breast carcinoma (2 papers, 2021 to 2023). "It has been shown that the expression level of 7SK was down-regulated in breast cancer, colon cancer, and Chronic Myelogenous Leukemia (CML)." (PMID 33868377, 2021). "The up-regulation of FOXJ3 in multiple types of cancers and the link between THRA and the breast cancer prognostic prediction suggest oncogenic functions of these two transcription factors, which is opposite to that of 7SK." (PMID 33868377, 2021).
amyotrophic lateral sclerosis (1 paper, 2022). Amyotrophic lateral sclerosis (ALS) is a neurodegenerative disease characterized by progressive muscular paralysis reflecting degeneration of motor neurons in the primary motor cortex, corticospinal tracts, brainstem and spinal cord. "Additionally, the hnRNPs associated with 7SK have been implicated in neurodegenerative conditions such as amyotrophic lateral sclerosis and frontotemporal lobar degeneration." (PMID 35856391, 2022).
cardiac hypertrophy (1 paper, 2007). "For example, in stress-induced cardiac hypertrophy or after exposure to UV radiation or transcription inhibitors, increased P-TEFb activity correlates with decreased 7SK RNA binding." (PMID 17925858, 2007).
chronic myeloid leukemia (1 paper, 2025). "The overexpression of 7SK has been reported to induce apoptosis by inhibiting cell proliferation in kidney cancer and was also found to be downregulated in chronic myeloid leukemia, breast, and colon cancer." (PMID 40788820, 2025).
retinoblastoma (1 paper, 2018). A malignant tumor that originates in the nuclear layer of the retina. "The results of microarray analysis showed that lncRNAs HOTAIR, CCAT1, DNM3OS, HIF1A‐AS1, MEG3 and 7SK expressions were up‐regulated, and lncRNAs PCAT1, MIR31HG, BCAR4, RRP1B and H19 were down‐regulated within retinoblastoma tissues." (PMID 30030888, 2018).
cancer (3 papers, 2021 to 2025). A tumor composed of atypical neoplastic, often pleomorphic cells that invade other tissues. "Like 7SK, nc886 primarily functions as an inhibitory molecule and has been implicated as a tumor suppressor in multiple cancers, though this too appears to be context-dependent." (PMID 36754845, 2023). "In view of the critical role of 7SK as a general regulator in gene transcription control and the suggestive dysregulation of 7SK in the previously reported cancer types, it would be of great interest to explore the biological function of 7SK in cancer and the underlying regulatory mechanism." (PMID 33868377, 2021). "In summary, the identification of 7SK in controlling TSCC progression expands our understanding of ncRNAs in cancer biology." (PMID 33868377, 2021). "Likewise, JMJD6 is also frequently altered in cancers with high expression and poor outcomes reported across many cancer contexts, potentially through mechanisms that include dysregulation of 7SK snRNP function." (PMID 36754845, 2023). "However, the biological function and mechanism of 7SK in cancer are largely unclear." (PMID 33868377, 2021).
tumor (3 papers, 2020 to 2023). "The association between tumors and reduced 7SK expression was further examined by using cultured tumor cell lines." (PMID 33868377, 2021). "Here, we showed that 7SK was down-regulated in 63% of the TSCC patients, and the expression level of 7SK was negatively correlated with the size of the tumor." (PMID 33868377, 2021). "All in all, we have reported a tumor-suppressive role of 7SK in TSCC and suggested a putative functional involvement of FOXJ3 and THRA in 7SK-mediated TSCC progression." (PMID 33868377, 2021). "Here, we identified 7SK acting as a novel tumor suppressor in TSCC, and suggested a putative functional involvement of FOXJ3 and THRA in 7SK-mediated TSCC progression." (PMID 33868377, 2021). "In functional assays, knockdown of 7SK in cell and xenograft experiments showed a tumor suppressor role of 7SK in TSCC." (PMID 33868377, 2021). "The down-regulated 7SK in TSCC patients and SCC15 cells indicates a tumor suppressor role of 7SK." (PMID 33868377, 2021). "It would be of great interest to demonstrate whether a directly functional link between FOXJ3/THRA and 7SK is involved in 7SK-mediated genes and 7SK-mediated tumor progression events in the near future." (PMID 33868377, 2021). "In TSCC, we found that 7SK was down-regulated in 63% of the 73 TSCC patients, and the down-regulated 7SK is correlated with the size of tumor." (PMID 33868377, 2021). "In addition, we have also identified a set of genes that are regulated in the opposite way by 7SK and FOXJ3/THRA, including four positive regulators in tumor migration (CXCL1, SYDE1, COL5A1, and HIF1A)." (PMID 33868377, 2021).
7SK also shares sentences with these, for which no sentence is quoted: colon cancer (1 paper); frontotemporal lobar degeneration (1); infection (1); kidney cancer (1); leukemia (1).